MYC (MYC proto-oncogene, bHLH transcription factor)
Diseases named in the same sentence as MYC in open-access papers (continued):
Sharing a sentence is not in itself a finding about the gene and the disease.
prostate carcinoma (continued). "First, we examined datasets from Oncomine and found that in prostate cancer patients relatively higher SIRT3 mRNA expression level was correlated with lower c-MYC expression." (PMID 26317998, 2015). "Oncoproteins like c-MYC robustly drive tumor development and are key players in various types of cancers including prostate cancer." (PMID 26317998, 2015). "Mechanistically, the ubiquitination level of c-MYC was reduced and degradation of c-MYC was attenuated by the activation of Akt in SIRT3 overexpressed prostate cancer cells." (PMID 26317998, 2015). "The half-life of c-MYC protein was significantly reduced in SIRT3 overexpressed prostate cancer cells, in comparison with the vector group." (PMID 26317998, 2015). "Reduced MYC was also reported following Hsp90 inhibition of neuroblastoma and prostate cancer cells, with suppression of the malignant phenotype and augmentation of chemotherapy response, respectively." (PMID 26556860, 2015). "Both amplification of the c-MYC oncogene and loss of the PTEN tumor suppressor are common features of human prostate cancer, and corresponding alterations in the mouse prostate result in adenocarcinomas." (PMID 26637281, 2015). "In conclusion, we demonstrate that when ERα is expressed in prostate cancer cells it regulates proliferation, MYC expression and glucose sensitivity." (PMID 25436982, 2015). "As adjudin is generally regarded as a safe molecule, future experiments to test the effectiveness of adjudin in prostate cancer and how it affects the Akt and c-MYC are warranted." (PMID 26317998, 2015). "Together these data demonstrated that SIRT3 induced oncoprotein c-MYC destruction by stimulating ubiquitin-mediated proteolysis in prostate cancer cells." (PMID 26317998, 2015). "Whereas primary tumors typically have simple gain of MYC due to an extra copy of 8q, metastases have more frequent regional MYC amplification, suggesting that MYC is more commonly involved in prostate cancer progression." (PMID 24062990, 2013). "This supposition is supported by a recent study showing that suppression of 4EBP1 expression resulted in re-sensitization of MYC-expressing prostate cancer cells to rapamycin-induced autophagy." (PMID 23383345, 2013). "GLIPR1 was shown to induce apoptosis in prostate cancer, and to promote MYC ubiquitination and degradation leading to suppression of cancer development." (PMID 23702334, 2013). "It is known that overexpression of MYC can immortalize human prostatic epithelial cells, so gain of function of MYC is clearly an oncogenic factor in human prostate cancer." (PMID 24062990, 2013). "For example, a neighboring gene, ATAD2, has been found to be a co-regulator of MYC and overexpression of ATAD2 has been associated with poor prognosis in breast, lung, and prostate cancers." (PMID 23393560, 2013). "I-BET762 potently reduced MYC expression in prostate cancer cell lines and a patient-derived tumor model with subsequent inhibition of cell growth and reduction of tumor burden in vivo." (PMID 24293458, 2013). "We have sought to explore MYC regulation in prostate carcinoma models in the response to I-BET762 treatment." (PMID 24293458, 2013). "Comparative Genomic Hybridization (CGH) studies have showed that gain of 8q, including 8q24 involving the MYC gene, is one of the most frequent alterations in prostate cancer." (PMID 24062990, 2013). "MYC reportedly promotes the metastatic phenotype by altering the epigenetic landscape of cancer cells, and is overexpressed in ~75% of advanced prostate cancer patients." (PMID 23782521, 2013). "PIM1 is weakly oncogenic in naive adult mouse prostatic epithelium, however, it synergizes with c-MYC to induce prostate cancer within 6-weeks." (PMID 23565217, 2013).
prostate carcinoma (continued). "MYC is a promising target in prostate cancer as demonstrated in the preclinical models of prostate cancer with antisense nucleotides." (PMID 24293458, 2013). "We also confirmed that FOXP3 is a direct transcriptional regulator of c-MYC, as described in prostate cancer." (PMID 23888189, 2012). "Molecular studies using specific FISH probes on CTCs from advanced prostate cancer patients have noted gains in AR and MYC, losses in PTEN, and evidence for ERG gene rearrangement." (PMID 22373240, 2012). "We also identified that salinomycin reduced the expression of prostate cancer oncogenes, MYC, AR and ERG, which are known to have antioxidative properties." (PMID 22215106, 2012). "We confirmed that in MCF7 cells RAD21 binds a putative enhancer for MYC that we termed C SNP, due to its proximity to a SNP associated with colorectal (CRC) and prostate cancer." (PMID 23145106, 2012). "In our set of matched primary prostate cancer specimens and normal prostate tissue, we found MYC and EZH2 elevation, and a positive correlation between the expression of the two genes." (PMID 21941025, 2011). "Activation of the PI3K signaling pathway, often via PTEN inactivation, and amplification of MYC are common genetic alterations in prostate cancer that correlate with high histological grade and poor prognosis." (PMID 21394210, 2011). "Here, we identify EZH2 as a target of the MYC oncogene in prostate cancer and show that MYC coordinately regulates EZH2 through transcriptional and post-transcriptional means." (PMID 21941025, 2011). "Cytokines can confer survival to tumor cells in xenografts derived from the Hi-MYC model, facilitating prostate cancer progression." (PMID 21394210, 2011). "The Lo-MYC transgenic mouse model recapitulates the molecular and histological phenotype of early human prostate cancer formation." (PMID 21941025, 2011). "Since increased MYC expression is an early feature of many human prostate cancers, these data have implications for treatment of human prostate cancers with PI3K-pathway alterations using mTOR inhibitors." (PMID 21394210, 2011). "Consistent with previous work, PI3K-pathway activation and MYC cooperate to accelerate progression of invasive prostate cancer, providing the rationale to characterize this cooperation more extensively and in a pure genetic background." (PMID 21394210, 2011). "MYC is required for androgen-dependent growth and following its ectopic expression can induce androgen-independent growth in prostate cancer cells." (PMID 22191037, 2011). "While this is not proven in humans, it is quite intriguing and further supports the relevance of MYC-based prostate cancer models driven by AR as highly relevant to the human disease." (PMID 20195545, 2010). "Prostate cancer induced by mouse prostate-specific overexpression of c-MYC oncogene demonstrated Pim1 mRNA upregulation, suggesting possible synergistic effect between two oncogenes." (PMID 20515470, 2010). "Further, they also showed that inactivating deletions or point mutations are fairly common in the FOXP3 gene in human prostate cancers and PIN lesions, and that FOXP3 can directly repress MYC mRNA levels." (PMID 20195545, 2010). "For example, MYC mRNA is overexpressed in the majority of all primary human clinical prostate cancer lesions." (PMID 20195545, 2010). "In prostate cancer, since a region encompassing the MYC locus (8q24) is amplified in late-stage/aggressive tumors, it is widely held that MYC is involved in disease progression." (PMID 20195545, 2010). "We compared prostate cancer with Burkitt's lymphoma because both harbor a recurrent translocation that leads to the over expression of two known oncogenes: c-MYC for Burkitt's lymphoma and ERG for prostate cancer." (PMID 20233430, 2010). "The c-MYC inhibitor 10058-F4 suppressed the tumorigenicity of Pim1-expressing prostate cancer cells." (PMID 20515470, 2010).
prostate carcinoma (continued). "Further, these studies support the concept that MYC-based mouse models of prostate cancer are useful “reagent mice” for studying the genetic, epigenetic, and microenvironmental changes that cooperate with MYC and lead to advanced and metastatic disease." (PMID 20195545, 2010). "MYC belongs to the cell cycle and apoptosis genes and becomes a key role in developing the prostate cancer." (PMID 20025723, 2009). "We report here our attempt to model these interactions in a new transgenic model of prostate cancer, focusing on the oncogene c-MYC and the tumor suppressor Pten (Phosphatase and tensin homolog), both of which are implicated in human prostate tumorigenesis." (PMID 19578399, 2009). "In a recent study it was shown that hypomethylation of the LINE 1 retrotransposon, as well as amplification of c-MYC can be used to predict tumour stage in prostate cancer." (PMID 18698372, 2008). "Concerning MYC protein expression, only two studies have been published for prostate cancer tissue so far." (PMID 17146477, 2007). "In conclusion, we showed that MYC immunostaining predicts Gleason score and furthermore pT-stage, which represents the two clinico-pathological parameters that correlate best with prostate cancer-specific survival." (PMID 17146477, 2007). "Clarifying both PNPLA2-dependent and -independent roles of ABHD5 in prostate cancer may uncover new insights into how lipid metabolism intersects with oncogenic signaling pathways such as c-MYC." (PMID 41349769, 2025). "Because c-MYC amplification drives the development of castration resistance, targeting the ABHD5–c-MYC axis may offer an effective therapeutic approach for advanced prostate cancer." (PMID 41349769, 2025). "Interestingly, in a mouse model of prostate cancer, overexpression of MYC dampened the androgen receptor transcriptional program via a mechanism involving cofactor redistribution." (PMID 40487451, 2025). "We demonstrate that pharmacological activation of ABHD5 with the synthetic ligand SR-3420 robustly suppresses c-MYC protein levels in two castration-resistant prostate cancer models expressing either wild-type or constitutively active, alternatively spliced androgen receptor variants." (PMID 41349769, 2025). "PIM1 promotes tumor growth in prostate cancer by interacting with MYC." (PMID 40018406, 2025). "The selection of VEGF, HAS3, and MYC as target genes for analysis was based on prior evidence indicating their predicted binding sites for miR-10a and their well-established roles in pathways relevant to prostate cancer biology." (PMID 41296417, 2025). "Furthermore, we demonstrated that TSPX binds directly to the promoter region of the MYC gene and suppresses the MYC expression in prostate cancer LNCaP cells." (PMID 39858622, 2025). "Glutamine metabolic reprogramming not only sustains tumor proliferation but also contributes to therapy resistance; inhibition of GLS or MYC sensitizes prostate cancer cells to radiotherapy, while autophagy enables glutamine-independent cells to withstand metabolic stress." (PMID 41179661, 2025). "Importantly, forced expression of stabilized MYC (MYCT58A) rescued NE transformation in prostate cancer models following treatment with a CDC7 inhibitor, implicating MYC as a key downstream effector of CDC7 during NE transformation." (PMID 39858043, 2025). "The effects of peroxisome proliferator-activated receptor gamma (PPARγ) in lipid metabolism, adipocyte differentiation, and apoptosis have been shown to be augmented by MYC inhibition, resulting in more well-differentiated phenotypes in both prostatic carcinoma and other neoplasms." (PMID 40422212, 2025).
prostate carcinoma (continued). "Additionally, the transcription factor MYC regulates prostate cancer-specific gene transcription by remodeling CTCF-mediated chromatin structure." (PMID 40475780, 2025). "LSD-i inhibits prostate cancer by targeting multiple oncogenic pathways, including MYC signaling." (PMID 40231263, 2025). "Third, beyond affecting the levels and phosphorylation of transcriptional regulators with central roles in prostate cancer growth and progression – AR, MYC, and BRD4 – CDKI-73 would blunt the oncogenic transcriptional programs activated by these factors via reducing pSer2-RNAPII." (PMID 39117800, 2024). "Interestingly, the loss of function of MerTK increases M1-like anti-tumor phenotypes and reduces M2-type pro-tumor macrophages in the high-MYC prostate cancer mouse model as well as decreases M2-mediated efferocytosis in prostate cancer LNCaP cells." (PMID 38891056, 2024). "The proto-oncogene c-MYC, commonly deregulated in prostate cancer." (PMID 38352401, 2024). "Moreover, their elevated expression levels were associated with poor survival outcomes, supporting DENND2D’s potential protective role through the suppression of MYC target genes in prostate cancer progression." (PMID 39857609, 2024). "In this review, we discuss the involvement of key TFs, including the E26 Transformation-Specific (ETS) Family (ERG and SPDEF), NF-κB, Activating Protein-1 (AP-1), MYC, and androgen receptor (AR), in prostate cancer while focusing on the molecular mechanisms involved in prostate cancer development." (PMID 38674385, 2024). "Interestingly, a similar mechanistic model has been proposed for prostate cancer, where MYC prevents differentiation by upregulating EZH226." (PMID 39184078, 2024). "To examine whether other exons that are regulated by hnRNPs H and F are also regulated by MYC, similarly to HRAS, we analyzed RNA-seq data from a prostate cancer model carrying a doxycycline-inducible MYC gene." (PMID 37399401, 2023). "Taken together, these results support the hypothesis that MYC activity controls mtDNA synthesis in prostate cancer cells." (PMID 37971875, 2023). "Tuft cell marker genes may be inherently upregulated in advanced prostate cancer, and further increase with progression with MYC as an oncogenic driver." (PMID 37386128, 2023). "mtDNA replication as a potential downstream target of MYC in prostate cancer." (PMID 37971875, 2023). "Furthermore (right), we found that FABP5 high mRNA expression is significantly correlated with MYC gene amplification, a well-validated driver gene of prostate cancer." (PMID 38201488, 2023). "In addition, the strong activity of EHMT1 in promoting prostate cancer metastasis suggests its potential involvement in regulating metastasis-related transcription factors, such as MYC." (PMID 37663929, 2023). "Indeed, MYC-independent ESRP1 amplification in early onset prostate cancer correlates with more advanced cancer histology and high mitotic activity of tumour cells, and is also predictive of a shorter time to disease recurrence." (PMID 37752235, 2023). "Notably, the MYC-controlled SE events were identified in a prostate cancer model derived from patient tissue that will exhibit very different transcriptional and splicing regulation from HepG2 cells." (PMID 37399401, 2023). "DNA FISH analysis identified hubs in multiple ecDNA+ human cancer cell lines, including COLO320-DM (MYC-amplified colorectal carcinoma), PC3 (MYC-amplified prostate cancer), HK359 (EGFR-amplified glioblastoma), and SNU16 (FGFR2- and MYC-amplified gastric cancer)." (PMID 35398879, 2022). "Our ChIP-seq analyses of genetically-modified prostate cancer cell lines suggested that KMT2A activity may positively mediate the tumorigenic function of MYC." (PMID 36181613, 2022).
prostate carcinoma (continued). "In prostate cancer, MYC remodels the chromatin structure to stimulate cell growth and promote oncogenic signaling via hyperacetylation and it has been shown that these oncogenic effects are partly mediated by the epigenetic reader protein, bromodomain extra-terminal (BET)." (PMID 35547880, 2022). "In addition, MYC is important in prostate cancer disparity in African-American (AA) men who are more frequently diagnosed with prostate cancer and have an aggressive disease." (PMID 35912174, 2022). "Overexpression of c-Myc (MYC), a master transcription factor and oncoprotein whose expression and function are tightly controlled under normal circumstances, is frequently observed in prostate cancer." (PMID 35562350, 2022). "Future studies are needed to validate these findings in larger cohorts, assess the viability of targeting ArA metabolism therapeutically, and determine whether ArA-based imaging agents demonstrate specific uptake in MYC-high/KMT2A-low prostate cancers." (PMID 36181613, 2022). "Besides, HMGB1 can trigger chemoresistance feature of prostate cancer cells via activating downstream targets such as MYC/c-Myc signaling." (PMID 35317831, 2022). "c-MYC (MYC) is a major driver of prostate cancer tumorigenesis and progression." (PMID 35562350, 2022). "The role of MYC in transcriptional reprogramming in prostate cancer remains poorly characterized." (PMID 35562350, 2022). "However, in c-MYC transgenic mice, c-MYC has been shown to promote prostate cancer carcinogenesis by boosting polyamine production through the transcriptional control of ODC." (PMID 36551330, 2022). "It is thus tempting to speculate that MYC decreases the reliance of prostate cancer cells on the canonical AR transcriptional program, therefore facilitating resistance to AR-targeted therapies." (PMID 35562350, 2022). "Hence, patients enrolled for future prostate cancer clinical studies with oral CUDC-907 should be tested for their MYC-status." (PMID 35582529, 2022). "This increased vulnerability may rely on the higher dependency on splicing of cancer cells with increased transcriptional activity, such as MYC-driven tumors and tumors displaying addiction to oncogenic transcription factors, such as the AR in prostate cancer." (PMID 35406598, 2022). "After topological enrichment, the most connected upregulated genes MYC, CDK1, CCNB1 etc. and the most connected downregulated genes EGFR, VEGFA, STAT3 etc. were categorized according to their highest degree count associated with prostate cancer." (PMID 35456461, 2022). "MUC1 was shown to induce BRN2, an NEPC-associated transcription factor, through MYC-mediated mechanism, and silencing MUC1 caused suppression of BRN2.This study highlights the significance of MUC1 in prostate cancer lineage plasticity, making it an attractive target for therapeutic inter-vention." (PMID 34298815, 2021). "In addition to the RNA families let-7, miR-34, and miR-145 mentioned before, the expression of the MYC gene in prostate cancer cells is controlled by miR-3667-3p and miR-33b." (PMID 34440124, 2021). "A direct correlation between CCAT1/2 and MYC transcript levels was found in prostate cancer." (PMID 33731118, 2021). "In addition, in prostatic cancer tissues, statistically significant positive correlations between MYC and HOXB13 mRNA levels was observed, while an independent group confirmed that the tumor-suppressive activity of MEIS1 was dependent on HOXB13." (PMID 34698191, 2021). "Initially 89Zr-Tf PET imaging was developed to annotate MYC in prostate cancer models." (PMID 34637026, 2021).